RNU1-40P (RNA, U1 small nuclear 40, pseudogene)
Gene: Small nuclear RNA gene on chromosome Y (25,928,979 to 25,929,142, forward strand). Ensembl gene ENSG00000252625.
Homologues: Orthologues: chimpanzee U1 (99% identical), chimpanzee U1 (98% identical), chimpanzee U1 (97% identical), macaque U1 (79% identical). Paralogues in human: RNU1-97P (100% identical), RNU1-128P (87% identical), RNU1-95P (87% identical), RNU1-41P (85% identical), RNU1-48P (85% identical), RNU1-89P (84% identical), RNU1-1 (84% identical), RNU1-2 (84% identical), RNU1-27P (84% identical), RNU1-28P (84% identical), RNU1-3 (84% identical), RNU1-4 (84% identical), and 133 more.